VCAN (versican)
Diseases named in the same sentence as VCAN in open-access papers (continued):
Sharing a sentence is not in itself a finding about the gene and the disease.
Vitreoretinopathy (5 papers, 2018 to 2022). Ocular abnormality characterized by premature degeneration of the vitreous and the retina that may be associated with increased risk of retinal detachment. "Furthermore, alteration of CRYAB is associated with cataract, and VCAN is associated with vitreoretinal degeneration." (PMID 33330132, 2020).
androgenetic alopecia (4 papers, 2021 to 2025). "The marked reduction of versican expression in dermal papilla cells from both androgenetic alopecia and vellus-like hair follicles suggests that versican is indispensable for promoting and sustaining hair growth in animal models." (PMID 41309381, 2025). "The expression of versican in androgenic alopecia is lower than in normal human hair follicles and previous studies have detected anagen-specific expression of versican in dermal papilla using immunofluorescence staining." (PMID 35453674, 2022). "Versican immunoreactivity in DPC is lost when HFs are affected by male pattern baldness." (PMID 33923738, 2021). "Research on androgenetic alopecia has shown that ADSC‐exosomes can promote DPC proliferation and increase the expression of cyclins, β‐catenin, versican, and BMP2." (PMID 40501302, 2025). "Patients affected by male pattern baldness were found to have little-to-no versican expression in the DP." (PMID 33923738, 2021).
autoimmune disease (4 papers, 2020 to 2025). A disorder resulting from loss of function or tissue destruction of an organ or multiple organs, arising from humoral or cellular immune responses of the individual to their own tissue constituents. "Versican is one of the extracellular matrix (ECM) proteoglycans that are increased during inflammatory processes in many diseases such as cardiovascular disease, autoimmune diseases, and several cancers." (PMID 37833287, 2023).
influenza (4 papers, 2016 to 2025). An acute viral infection of the respiratory tract, occurring in isolated cases, in epidemics, or in pandemics; it is caused by serologically different strains of viruses (influenzaviruses) designated A, B, and C, has a 3-day incubation period, and usually lasts for 3 to 10 days. "Col1a2/Vcan−/− and WT mice were infected with 20 PFU of IAV and monitored for up to 15 dpi to investigate the impact of mesenchymal-derived versican deficiency on influenza infection and disease." (PMID 40766376, 2025). "The highest density of versican expression observed in untreated and influenza-infected mice was in mesenchymal cells, identified by Col1a1 and Acta2 expression." (PMID 40766376, 2025). "On-going studies in our laboratory using multiple models of cell-specific versican deficiency will aid in a better understanding of the contextual nature of versican’s role in the pulmonary innate immune response to influenza infection." (PMID 39400584, 2024). "We also assessed CD8+ T cell numbers in MLN of influenza-infected Adamts5-/-Vcan+/hdf (versican reduced) mice to determine resumption of egress." (PMID 27855162, 2016). "Additionally, we stained influenza-infected lung with antibodies specific for versican and versikine." (PMID 27855162, 2016). "Careful analysis revealed comparable numbers of total CD8+ T cells and influenza-specific CD8+NP366-372+ and DbPA224-233+ (by tetramer and ICS) in the MLN of Adamts5-/-Vcan+/hdf (versican reduced) and C57.BL6 control mice." (PMID 27855162, 2016).
invasive breast carcinoma (4 papers, 2007 to 2025). A carcinoma that infiltrates the breast parenchyma. "The presence of two EGF-like motifs in versican G3 given the increasing importance known clinically regarding the role of EGF receptors in invasive breast carcinoma is of interest." (PMID 17662123, 2007). "The Breast Invasive Carcinoma TCGA PanCancer Atlas dataset was used to identify 48 VPP cases and 66 VPW cases based on the expression of VCAN, ADAMTS4, and TIMP3." (PMID 40361362, 2025).
lymph node metastasis (4 papers, 2021 to 2023). "Expression of versican is linked to lymph node metastasis, tumour size, infiltration depth, and vascular space involvement." (PMID 36982551, 2023). "In our study, versican in plasma and plasma exosomes was evaluated using ELISA and shown to be linked to TNM stage, lymph node metastasis, distant metastasis, and mutation (all P < 0.05)." (PMID 37259101, 2023). "The results showed that the rate of high expression of VCAN in BLCA was 70.3% (293/417), and high expression of VCAN was correlated with the number of tumors, invasion depth, lymph node metastasis, distant metastasis, and histological grade." (PMID 33604385, 2021). "Our present study revealed a high expression of VCAN which correlated with invasion depth, lymph node metastasis, and distant metastasis." (PMID 33604385, 2021). "The levels of plasma versican were positively correlated with TNM stage (T1–T4) (r = 0.589, P < 0.0001) and lymph node metastasis (N = 0 or N ≥ 1) (r = 0.522, P < 0.0001)." (PMID 37259101, 2023). "Similarly, plasma exosomal versican in NSCLC patients was positively correlated with TNM stage (r = 0.493, P < 0.0001) and lymph node metastasis (r = 0.348, P = 0.0002)." (PMID 37259101, 2023). "Hence, tumor size, lymph node metastasis, lymphovascular invasion, distant metastasis, depth of invasion, TNM stage, and VCAN expression were included in Cox's proportional hazard regression model." (PMID 33604385, 2021). "High expression of VCAN was detected in 66.0% (208/315) BLCA patients without lymph node metastasis, which was lower than that with lymph node metastasis (83.3%, 85/102, χ2 = 11.039, P = 0.001)." (PMID 33604385, 2021). "It was indicated that distant metastasis (P = 0.042), depth of invasion (P = 0.036), TNM stage (P < 0.001), and VCAN expression (P = 0.001) were independent prognostic factors for patients with BLCA, whereas tumor size, lymph node metastasis, and lymphovascular invasion were not." (PMID 33604385, 2021).
mesothelioma (4 papers, 2014 to 2024). A usually malignant and aggressive neoplasm of the mesothelium which is often associated with exposure to asbestos. "Importantly, versican-deficient mesothelioma cells polarised co-cultured macrophages to an M1 phenotype, suggesting VCAN targeting may promote a more favourable immune landscape." (PMID 38791926, 2024). "In mesothelioma, tumor cell-derived versican promotes both macrophage migration and their polarization toward the M2 phenotype." (PMID 33466303, 2021). "Versican modulates TAM phenotype in mesothelioma, where high levels correlate with poor outcome." (PMID 38791926, 2024). "In addition, VCAN stimulated mesothelioma growth by weakening the antitumor activity of macrophages." (PMID 33015179, 2020).
Obesity (4 papers, 2020 to 2024). Accumulation of substantial excess body fat. "Fas cell surface death receptor (Fas), versican (Vcan), T-box transcription factor 21 (Tbx21), angiotensin I converting enzyme (Ace), and serpin family E member 2 (Serpine2), metabolic markers associated with obesity, were increased in the obese group." (PMID 38728395, 2024). "In that study, the expression of three PGs was altered as a result of obesity: serglycin, versican, and asporin." (PMID 37108048, 2023). "Genetic correlations with obesity and glucometabolic traits were observed, and VCAN was highlighted as a plausible candidate gene in the women-only locus." (PMID 31801372, 2020). "We subsequently have shown that versican derived from adipocytes and biglycan derived from adipose tissue macrophages were increased in obesity." (PMID 32970631, 2020).
osteoarthritis (4 papers, 2014 to 2025). A noninflammatory degenerative joint disease occurring chiefly in older persons, characterized by degeneration of the articular cartilage, hypertrophy of bone at the margins and changes in the synovial membrane. "ADAMTS4-mediated aggrecan degradation in articular cartilage is widely recognized as a primary etiological factor in the pathogenesis of osteoarthritis, while its cleavage of both aggrecan and versican plays a crucial role in the instability of atherosclerotic plaques." (PMID 40002887, 2025). "The degradation of versican and aggrecan by ADAMTS (a disintegrin and metalloprotease with thrombospondin motifs) proteases is essential in ECM reorganization in both pathological and physiological processes, including osteoarthritis, atherosclerosis, and regulation of cardiac organogenesis." (PMID 24595230, 2014).
ovarian tumor (4 papers, 2013 to 2024). "The pro-angiogenic macrophage subpopulation (Mac_Angio, n = 3108) displayed high expression of genes associated with angiogenesis, such as VEGFA, VCAN, and EREG, and was found enriched in lung and ovarian tumors." (PMID 38972873, 2024). "According to the HPA, high expression of CAV2, COL11A1, DNAJB4, THY1 and VCAN decreased the 5-year survival for breast, CNS, colon, kidney, lung and ovarian tumors." (PMID 37986165, 2023). "Further studies revealed that the TGF-β-rich ovarian tumor microenvironment up-regulates the production of versican (VCAN), a large extracellular matrix proteoglycan, in CAFs." (PMID 26751490, 2016). "In summary, we have found that versican V1 enhances hCAP18/LL-37 expression in macrophages through activation of TLR2 and subsequent vitamin D-dependent mechanisms which promote ovarian tumor progression in vitro." (PMID 23424670, 2013).
renal carcinoma (4 papers, 2017 to 2021). A carcinoma arising from the epithelium of the renal parenchyma or the renal pelvis. "VCAN knockdown significantly reduced the proliferation of renal cancer cells and increased apoptosis, which is linked to the changes of several TNF signaling related genes such as TNFα, BID and BAK." (PMID 33836688, 2021). "Furthermore, this might point out that versican and leptin might increase the metastatic ability of renal cancer cells." (PMID 29212223, 2017).
thyroid cancer (4 papers, 2018 to 2021). "A few studies have shown that the expression of VCAN was upregulated in thyroid cancer tissues, and it was associated with malignant behavior of thyroid carcinoma." (PMID 33564303, 2021). "Moreover, miR-135a-5p regulated cell proliferation, migration and invasion in thyroid carcinoma cells by targeting VCAN 3′UTR." (PMID 32099526, 2020).
aneurysm (3 papers, 2018 to 2022). Bulging or ballooning in an area of an artery secondary to arterial wall weakening. "LRP1, which has been involved in aneurysm pathology in both humans and mice, appears to be linked to ADAMTS-5 and ADAMTS-5–mediated versican cleavage." (PMID 29622560, 2018). "They showed that ADAMTS-4 deficiency resulted in reduced aneurysm and dissection formation, with associated maintenance of normal elastin fibre arrangements, reduced inflammatory cell infiltration and apoptosis, with reduced versican degradation." (PMID 36012466, 2022). "An increase in RNA levels of versican but not biglycan was also observed in aneurysm patients compared to control." (PMID 36012466, 2022). "Although differences in versican abundance have been reported in human abdominal aortic aneurysms, versikine has not been localized yet in human AsAo aneurysms." (PMID 29622560, 2018).
Cirrhosis (3 papers, 2011 to 2023). A chronic disorder of the liver in which liver tissue becomes scarred and is partially replaced by regenerative nodules and fibrotic tissue resulting in loss of liver function. "VCAN, an extracellular matrix component, has been shown to also be involved in fibrotic deposition in the liver, which may limit its applicability as a diagnostic marker for HCC in the setting of cirrhosis." (PMID 37006626, 2023). "Thus, VCAN may contribute to the progression of chronic liver disease to LF, cirrhosis and liver cancer." (PMID 36275632, 2022). "It is interesting to note that hub proteins are usually targeted, such as LCK, STAT1 and VCAN in Normal-Cirrhosis network, LCK in Cirrhosis-Dysplasia network, CDC2 and NDC80 in Dysplasia-Early HCC network and Early-Advanced network." (PMID 21824427, 2011).
fibrosis (3 papers, 2022 to 2025). the formation of excess fibrous connective tissue in an organ or tissue in a reparative or reactive process. "In this study, we have examined versican during cardiac fibrosis development in a murine pressure overload model and in patients with cardiomyopathies." (PMID 38076279, 2023). "In addition, CS PGs, including VCAN and CD44, have been implicated in both hepatic fibrosis and HCC formation." (PMID 36923282, 2022). "The spatial analysis revealed a colocalization of these VCAN-expressing CAFs with regions of intense tumor fibrosis, indicating their potential contribution to the high-fibrotic phenotype of the TME in Fibrosis+ LM." (PMID 41258075, 2025). "By contrast, VCAN_eCAF, substantially expanded in fibrotic regions (Fibrosis+ LM) and highly expressing core ECM genes (LUM, VCAN and collagens), may constitute an activated, terminal state that dominates the pathological ECM remodeling." (PMID 41258075, 2025). "Since the cleavage of versican was prominent towards the late phase of fibrosis development in pressure overload, we also examined DPEAAE in cardiomyopathy patients with established fibrosis." (PMID 38076279, 2023).
hair loss (3 papers, 2013 to 2025). "In men, alopecia was associated with a significant (P < 0.001) increase in the amounts of versican+ stromal cells and human podoplanin+ lymphatic vessels." (PMID 24455724, 2013). "Overall, we propose that JAM-A 3′ UTR forms a feedback loop with VCAN and miR-221–3p to regulate hDPC maintenance, proliferation, and differentiation, which may lead to developing new therapies for hair loss." (PMID 36132055, 2022). "Our findings suggest that VCAN may facilitate hair germ formation during the early stages of hair follicle development, which may provide valuable insights for the development of treatments for hair loss." (PMID 41380997, 2025).
Hypertension (3 papers, 2019 to 2025). The presence of chronic increased pressure in the systemic arterial system. "In TAD patients with hypertension decorin, versican core protein and basement membrane-specific heparan sulphate proteoglycan core protein precursor were downregulated." (PMID 36012466, 2022). "Moreover, we had a number of suggestive genes arise from our vascular tissue data, highlighted as having specific effects on the ECM including TIMP2, PSAP, FN1, VCAN, and LOX, each of which have been previously implicated in hypertension." (PMID 30931314, 2019).
leiomyosarcoma (3 papers, 2020 to 2026). An uncommon, aggressive malignant smooth muscle neoplasm, usually occurring in post-menopausal women. "In fact, strawberry treatment slightly decreased the expression of collagen1a1 and significantly decreased the expression of fibronectin (p = 0.0312), versican (p = 0.0312), and activin A (p = 0.0312) in the spheroids of leiomyosarcoma." (PMID 37299521, 2023). "Notably, a strong correlation between VCAN and ERK5 expression, both at mRNA and protein levels, emerged in biopsies from leiomyosarcomas and undifferentiated pleomorphic sarcomas." (PMID 41800245, 2026).
metastatic cancer (3 papers, 2009 to 2024). A carcinoma which has spread from the original site of growth to another anatomic site. "VCAN belongs to the proteoglycan family and encodes chondroitin sulfate proteoglycan, which is a highly conserved structural component in ECM and is expressed in invasive and metastatic cancers." (PMID 31824575, 2019).
muscular dystrophy (3 papers, 2017 to 2025). Muscular dystrophy (MD) refers to a group of more than 30 genetic diseases characterized by progressive weakness and degeneration of the skeletal muscles that control movement. "In conclusion, our findings demonstrate the biological significance of versican as a therapeutic target in muscular dystrophy and highlight the positive, yet complex effects of versican reduction in dystrophic mdx mice." (PMID 32632164, 2020). "A better understanding of versican function in muscular dystrophy is needed if progress is to be made in targeting the dysregulated ECM, which is a hallmark of DMD pathology." (PMID 29211034, 2017). "Versican is a provisional matrix protein implicated in fibrosis and inflammation in various disease states, yet its role in the pathogenesis of muscular dystrophy is not known." (PMID 32632164, 2020). "Altogether, these observations suggest a novel mechanism by which excess versican could compromise regenerative myogenesis in muscular dystrophy." (PMID 29211034, 2017).
pulmonary arterial hypertension (3 papers, 2024 to 2025). Pulmonary arterial hypertension (PAH) is a group of diseases characterized by mean pulmonary artery pressure >20 mmHg and elevated pulmonary arterial resistance leading to right heart failure. "VCAN is dramatically elevated in the subendothelial space in many vascular diseases, including pulmonary hypertension and atherosclerotic plaques, where it has been associated with the accumulation and retention of LDL." (PMID 40623650, 2025). "As VCAN is an extracellular matrix proteoglycan that is dramatically increased in vascular lesions of pulmonary arterial hypertension, this case demonstrates that VCAN is also involved in the pathophysiology of PTTM." (PMID 39205715, 2024).
sarcopenia (3 papers, 2017 to 2025). Progressive decline in muscle mass due to aging which results in decreased functional capacity of muscles. "In a large meta-analysis of genome-wide association studies for lean mass, VCAN loci (rs2287926) was identified and successfully replicated for whole body lean mass, and was important for sarcopenia diagnosis." (PMID 36788507, 2023). "Therefore, we suggested that the decreased expression of ADAMTSs, especially ADAMTS4, could contribute to the compromised regenerative potential of skeletal muscle stem cells by promoting fibronectin and versican deposition in CS-exposed mice, thereby leading to COPD-related sarcopenia." (PMID 40002887, 2025).
schizophrenia (3 papers, 2014 to 2022). A major psychotic disorder characterized by abnormalities in the perception or expression of reality. "Recently, it was shown that some CSPGs members like aggrecan, versican, and neurocan were strongly involved in brain disorders like bipolar disorder (BD), schizophrenia, and ADHD." (PMID 24955366, 2014).
serous ovarian cancer (3 papers, 2011 to 2020). "Our recent studies have confirmed the presence of high CD44 immunostaining particularly in the peritumoral stroma of serous ovarian carcinomas which was associated with high HA and versican expression." (PMID 21541039, 2011). "Most recently, VCAN has been included in a prognostic gene signature in high grade serous ovarian cancer." (PMID 33019700, 2020). "Immunohistochemistry studies in our laboratory have confirmed that versican is increased in the stromal compartment of serous ovarian carcinoma compared to the stroma of normal ovaries or benign ovarian tumors." (PMID 21541039, 2011). "Our recent studies have confirmed the presence of high HA levels in the peritumoral stroma of serous ovarian carcinomas which correlate with CD44 and versican expression." (PMID 21541039, 2011).
tendinopathy (3 papers, 2013 to 2015). "The greater decrease in ADAMTS4 distant from the lesion, and increased VCAN predominantly proximal, suggest additional complex regulatory control of injury-induced tendinopathy." (PMID 25837713, 2015). "While increased, unchanged and decreased VCAN mRNA have been reported in human tendinopathy, versican protein content is routinely increased as in the current equine model, and may also contribute to increased toluidine blue staining." (PMID 25837713, 2015). "Those that have include versican, in which AS may contribute to changes in ECM structure and function in tendinopathies; lubricin, which is location-dependent; and insulin-like growth factor 1, which is mechanical stress-dependent." (PMID 25888722, 2015). "However, MMP1, MMP13, MMP10, ADAMTS5, TIMP3, versican, aggrecan, biglycan, decorin, fibronectin, fibrillin and COMP showed an opposite response with strain compared to tendinopathy." (PMID 23830915, 2013).